SMYD2 (SET and MYND domain containing 2)
Diseases named in the same sentence as SMYD2 in open-access papers (continued):
Sharing a sentence is not in itself a finding about the gene and the disease.
cancer (67 papers, 2015 to 2026). A tumor composed of atypical neoplastic, often pleomorphic cells that invade other tissues. "Aberrant expression of SMYD2 is closely associated with several diseases, including cardiovascular diseases and cancer." (PMID 40777131, 2025). "SMYD2 is upregulated in many types of cancer and is associated with a marked decrease in overall survival and accelerated disease progression." (PMID 38740816, 2024). "This aligns with the fact that SMYD2 is overexpressed in various cancers and associated with poor patient outcomes." (PMID 39677743, 2024). "In this comprehensive analysis, various bioinformatics databases and tools were used to elicit the SMYD2 expression, prognostics value, DNA methylation, mutation, CNAs, and correlated genes of SMYD2 in various human cancers." (PMID 37971632, 2023). "From here, we selected only the cancers reported with the overexpression of SMYD2 and associated with cancer progression." (PMID 37971632, 2023). "SMYD2 is involved in a wide range of cancers, causing cell proliferation through mechanisms that include various functionally independent cellular processes and nonhistone lysine substrates." (PMID 36838987, 2023). "For example, SMYD2 methylates retinoblastoma tumor suppressor protein (RB), which regulates the cell cycle and is mutated in several kinds of cancer." (PMID 36975803, 2023). "Results showed that a lower SMYD2 expression group has been significantly associated with a higher survival rate in the maximum type of cancer patients for both OS and DFS." (PMID 37971632, 2023). "Since the abnormal expression or dysfunction of SMYD2 is often closely associated with a variety of diseases, SMYD2 is regarded as a promising candidate for the treatment of diseases, such as cardiovascular disease and cancer." (PMID 36270984, 2022). "High expression of SMYD2 has been shown to be associated with poor prognosis in several cancers, including CRC." (PMID 35022391, 2022). "A recent study reported overexpression of SMYD2 in cancer vs. normal tissue, and associated higher expression of SMYD2 with enhanced proliferation in HGSC." (PMID 32133296, 2020). "SMYD2 has been shown to suppress the activation of macrophages, which have also been implicated in the immune response to cancer." (PMID 29856759, 2018). "Our analysis revealed that missense mutations in human cancer can have a substantial impact on the lysine methylation signaling network for SMYD2." (PMID 30498785, 2018). "Missense mutations that strengthen, weaken, create, or destroy new SMYD2 substrates are abundant in human cancer cells." (PMID 30498785, 2018). "SMYD2 protein levels are elevated in various cancer types, and overexpression of SMYD2 in cancer cell lines promotes phenotypes associated with oncogenic transformation." (PMID 26988419, 2016). "SMYD2 is overexpressed in various cancers and is associated with their functions." (PMID 39482529, 2024). "Moreover, the possible link between genetic variants of SMYD2 and survival prognosis across all TCGA cancer was also investigated." (PMID 37971632, 2023). "Abnormal function of SMYD2 is closely associated with cancer and kidney disease." (PMID 37673879, 2023). "Finally, we used the list of associated genes with SMYD2 in various cancers for an ontology-level analysis to identify the putative signaling pathways." (PMID 37971632, 2023). "Increased activity of the SMYD2 protein is associated with more aggressive growth in several cancer types, and Kwangho Kim of the Korea Research Institute of Bioscience and Biotechnology, Daejeon, and colleagues have linked heightened SMYD2 expression with poor prognosis in NSCLC patients." (PMID 37121971, 2023).
cancer (continued). "Dysregulation of SMYD2 has been associated with several diseases including cancer." (PMID 35022391, 2022). "We next turned our attention to predicting how reported missense mutations in primary human cancer sequencing datasets might rewire lysine methylation signaling networks because of substitutions within SMYD2 substrate motifs." (PMID 30498785, 2018). "Histone methyltransferase SET and MYND domain-containing protein 2 (Smyd2) is associated with multiple diseases including cancer and inflammatory diseases, but whether it is involved in endothelial cell senescence and aging-related cardiovascular diseases has not been directly proved." (PMID 36585926, 2022). "Although reports show that SMYD2 methylates key cancer proteins and suggest that this methyltransferase may be implicated in cancer, they have not as a whole revealed a driver substrate and/or mechanism of SMYD2 oncogenesis." (PMID 25825497, 2015). "SMYD2 has been reported to act as an oncogene in various cancers such as rectal cancer, lung cancer, and prostate cancer." (PMID 40391402, 2025). "The Human Cancer Genome Atlas (TCGA) database was analyzed using the UALCAN GEPIA to investigate the differential expression patterns of SMYD2, STAT3, and EZH2 across various BC subtypes." (PMID 40807332, 2025). "HSP90 was methylated by SMYD2 at lysine 531 and 574, thereby accelerating the proliferation of cancer cells." (PMID 40777131, 2025). "Previous reports have described SMYD2 expression and its inclusion in prognostic signatures for cancer diagnosis." (PMID 39482529, 2024). "Given SMYD2’s role in various cancers, this work opens exciting avenues for designing specific allosteric inhibitors with reduced off-target effects." (PMID 39677743, 2024). "Our analysis identifies SET and MYND Domain Containing 2 (SMYD2) as the top candidate, a lysine methyltransferase overexpressed in various cancers and previously linked to cancer pathogenesis." (PMID 38296970, 2024). "SMYD2 plays a significant role in metastasis by regulating the expression of various cancer-related genes." (PMID 39482529, 2024). "In normal cells, ectopic expression of SMYD2 had a modest effect, but this became more pronounced when cells faced cytokinetic challenges which are common in cancer cells." (PMID 38740816, 2024). "The regulation of SMYD2 expression controls the growth and metastasis of cancer, indicating that SMYD2 is a therapeutic target for cancer treatment." (PMID 39482529, 2024). "Our study raises intriguing functional questions about the overexpression of SMYD2 in various cancer types." (PMID 38740816, 2024). "In conclusion, the discovery of this novel allosteric site not only reveals a new biochemical mechanism for SMYD2 regulation but also opens new therapeutic avenues for targeting SMYD2 in cancer." (PMID 39677743, 2024). "Inhibiting SMYD2 with SMYD2-specific inhibitors effectively suppresses metastasis, which is the most problematic aspect of cancer treatment, thus increasing the success of cancer treatment." (PMID 39482529, 2024). "Outside of cancer field, SMYD2 has been reported to play a role in regulating titin stability in striated muscle." (PMID 39609254, 2024). "Future studies will evaluate the CHMP2B methylation status in normal and cancer tissues to demonstrate the potential pro-oncogenic impact of ESCRT-III methylation signaling mediated by SMYD2." (PMID 38740816, 2024). "The research presented in this review indicates that SMYD family members are important targets for cancer therapy, with SMYD2 and SMYD3 proposed as more effective targets for cancer treatment." (PMID 39482529, 2024). "Recent studies have also investigated the crucial role of SMYD2 in inhibiting resistance to chemotherapy in various cancers." (PMID 39482529, 2024).
cancer (continued). "The SMYD2 was overexpressed in most types of cancer (p < 0.001) as compared to the corresponding normal tissues." (PMID 37971632, 2023). "In conclusion, SMYD2 would be a possible biomarker and a significant drug target for the prevention and management of human cancers." (PMID 37971632, 2023). "In the current study, investigators used TCGA data to determine the potential carcinogenic effect of SMYD2 in 11 cancer types." (PMID 37971632, 2023). "To explore the critical efficiency of SMYD2 in the survival of various cancer cases, we used GEPIA2 to evaluate survival data and establish an association between cancer patient survival and RNA expression SMYD2." (PMID 37971632, 2023). "Here, the GEPIA2 program was used to perform a statistical correlation between SMYD2 expressions and overall/disease-free survival rate of cancer patients." (PMID 37971632, 2023). "In the present analysis, we systematically explored the SMYD2 expression and its clinical outcomes to evaluate its potential marker for cancer treatment." (PMID 37971632, 2023). "SMYD2 is an emerging target in cancer research, and its high expression is believed to be involved in poor-prognosis cancers." (PMID 37513898, 2023). "SMYD2 is closely related to the occurrence and development of multiple cancer types, including cervical, colon, and esophageal cancer." (PMID 36816359, 2023). "This analysis suggested that SMYD2 has a promoting role in the occurrence and progression of cancer." (PMID 37971632, 2023). "SMYD2, which is expressed in both cytoplasm and nucleus in cancer cells, is also investigated in its function on dimethylation of H3K4 or H3K36 to suppress cell proliferation." (PMID 37673879, 2023). "The overexpression of SMYD2 was present in tumor tissues of all cancer types except a few compared to normal tissues." (PMID 37971632, 2023). "It has been shown that SMYD2-dependent methylation of RB1 at K810 promotes cell cycle progression in cancer cells." (PMID 37894343, 2023). "In a related study, AZ505, another strong SMYD2 inhibitor, blocked SMYD2 and significantly reduced cancer cell proliferation, migration, and invasion in an in vitro and in vivo xenograft mice model." (PMID 37513898, 2023). "Findings revealed that higher expression of SMYD2 was significantly correlated with cancer incidents." (PMID 37971632, 2023). "Our integrated analysis shows that SMYD2 would be a potential biomarker for a wide range of cancers." (PMID 37971632, 2023). "Here, we used various algorithms such as CIBERSORT, TIMER, XCELL, MCPCOUNTER, CIBERSORT-ABS, EPIC, and QUANTISEQ to study the correlation between immune cell infiltration and SMYD2 expression in multiple cancers types." (PMID 37971632, 2023). "SMYD2 has been demonstrated for several cancers as a prognostic indicator for disease severity and progression." (PMID 36838987, 2023). "The expression of SMYD2 was significantly correlated with tumor purity and immunocyte infiltration in six cancer types." (PMID 37971632, 2023). "RANi-induced SMYD2 silencing within TNBC cells or AZ505 (an inhibitor of SMYD2)-mediated SMYD2 inhibition remarkably decreases in vivo cancer development." (PMID 36188615, 2022). "SMYD2, which is essential for normal organismal development, was found to be dysregulated in cardiovascular disease and cancer, and overexpression often correlated with a lower survival rate." (PMID 35455942, 2022). "Previous studies have identified that methyltransferase SET and MYND domain-containing protein 2(SMYD2) is responsible for the pathogenesis of numerous types of cancer." (PMID 36611819, 2022).
cancer (continued). "Namely, the expression levels of ATP1A2, CILP, and THSD4 were downregulated in cancer tissues compared with paracancerous tissues, whereas the expression levels of SMYD2 and GAPDHP1 were upregulated." (PMID 35498536, 2022). "The Cancer Genome Atlas (TCGA) was analyzed through UALCAN’s GEPIA to investigate the differential expression pattern of SMYD2 in various types of cancer and, more specifically, PC types." (PMID 35884603, 2022). "SMYD2 plays a pivotal role in cancer through the induction of cell proliferation, migration, and invasion, as well as inhibition of apoptosis." (PMID 35884603, 2022). "Previous research has shown that SMYD2 is involved in the occurrence and progression of a variety of cancers." (PMID 35498536, 2022). "To explore the role of SMYD2 in cancer metastasis, we used a tail vein injection mouse model and detected lung metastasis through IVIS." (PMID 33935284, 2021). "The enrichment of EP300 or SMYD2 in the promoter region of LINC01605 were much higher in cancer tissues than that in ADJ tissues." (PMID 34544413, 2021). "We then confirmed the subcellular localization of EP300 and SMYD2 in cancer tissues using fluorescence co-localization experiments, and we found that SMYD2 had co-localization with EP300 in the nucleus in cancer tissues." (PMID 34544413, 2021). "We previously demonstrated that the second member of the SMYD family, SMYD2, is widely expressed during normal embryogenesis but also in several cancers." (PMID 32408548, 2020). "While our understanding of the role of SMYD2 in cancers remains incomplete, its function in embryogenesis is even less understood." (PMID 32408548, 2020). "The overlap between SMYD2 and the WNT pathway, particularly given their independent associations with such a wide range of cancers, merits immediate further investigation." (PMID 32408548, 2020). "Further investigation of the functions of SMYD2 in these contexts will expand our understanding of mammalian development and improve our clinical management of cancer." (PMID 32408548, 2020). "While our understanding of the role of SMYD2 in cancers is certainly incomplete and requires further investigation, its function in embryogenesis is even less understood." (PMID 32408548, 2020). "In vivo and in vitro experiments were performed to explore the function of SMYD2 in cancer progression." (PMID 31548876, 2019). "Then, we discuss the discovery, structure, inhibitors, roles, and molecular mechanisms of SMYD2 in distinct diseases, with a focus on cardiovascular disease and cancer." (PMID 31370883, 2019). "Different in vivo studies have demonstrated the role played by Smyd2 in cancer initiation and progression." (PMID 31069954, 2019). "The important role played by Smyd2 in cancer biology has spurred the development of cell‐active inhibitors." (PMID 31069954, 2019). "Among the SMYD enzymes, SMYD2 and SMYD3 have been implicated as targets for a variety of cancer indications." (PMID 29856759, 2018).
cancer (continued). "To further clarify the significance of SMYD2‐mediated methylation on EML4‐ALK protein on the growth of cancer cells, we examined the effect of exogenous introduction of lysine‐substituted EML4‐ALK proteins into two NSCLC cells with EML4‐ALK." (PMID 28370702, 2017). "After treatment with a SMYD2 inhibitor, significant reduction of nuclear β-catenin and subsequent induction of cancer cell death are observed." (PMID 28915556, 2017). "AHNAK2 has also been reported to be involved in human esophageal squamous carcinoma (ESCC) by regulating protein lysine mono-methyltransferase SMYD2, which is overexpressed or amplified in various types of cancers." (PMID 28423668, 2017). "Genetically engineered murine models of cancer further emphasize tissue- specific and oncogene-specific roles of SMYD2 in tumorigenesis." (PMID 28187429, 2017). "A series of studies pointed to the potential involvement of Smyd2 and Smyd3 in various human cancers." (PMID 27655694, 2016). "SMYD2 (SET and MYND domain 2) is a lysine methyltransferase (KMT) that has been implicated in cancer development." (PMID 26988419, 2016). "Immunoblots from the pancreata of these Kras mutant mice showed that SMYD2 levels increased with cancer progression." (PMID 26988419, 2016). "Smyd2 is over-expressed in several cancer types and was shown to be limiting for tumor development in the pancreas." (PMID 27655694, 2016). "Here we investigate the function of SMYD2 in the lethal cancer pancreatic ductal adenocarcinoma (PDAC) using mouse and cellular models." (PMID 26988419, 2016). "In conclusion, the results in this study show that LLY-507 is a cell-active and selective inhibitor of SMYD2, and serves as a valuable chemical probe to elucidate the role of SMYD2 in cancer and other biological processes." (PMID 25825497, 2015). "The Cancer Genome Atlas analysis was also performed to identify tumor types showing overexpression of SMYD2 at the transcript level." (PMID 25825497, 2015). "SMYD2 plays an important role in various diseases, including cardiac disease and cancers." (PMID 40777131, 2025). "In addition, reports on SMYD2 inhibitors have highlighted the potential of SMYD2 as an important therapeutic target in various cancers." (PMID 39482529, 2024). "The widespread pro-oncogenic role of SMYD2 suggests that this methyltransferase may regulate a common biological process that contributes to tumor development across a diverse range of cancers." (PMID 38740816, 2024). "In this section, we describe how SMYD2 overexpression, which is observed in various cancers, influences proliferation, metastasis, drug resistance, and other processes through the regulation of cancer targets." (PMID 39482529, 2024). "Thus, SMYD2 plays an important role in inhibiting resistance to cancer chemotherapy, and simultaneous treatment with SMYD2 inhibitors during chemotherapy is expected to increase the effectiveness of chemotherapy." (PMID 39482529, 2024). "Recent reports have indicated increased SMYD2 expression in various cancers." (PMID 39482529, 2024). "Additionally, the identification of nonhistone methylation of various cancer-related genes suggests that SMYD2 is an important therapeutic target for cancer treatment." (PMID 39482529, 2024). "SMYD2 can methylate lysine residues in both histone and non-histone proteins associated with cancer, thereby playing a crucial role in tumorigenesis." (PMID 39131609, 2024). "Here, we propose that methylation could trigger the premature exit from the abscission checkpoint in cancer cells with elevated SMYD2 expression." (PMID 38740816, 2024).